CTLA4 (cytotoxic T-lymphocyte associated protein 4)
Diseases named in the same sentence as CTLA4 in open-access papers (continued):
Sharing a sentence is not in itself a finding about the gene and the disease.
tumor (continued). "At present, programmed death‐1 (PD‐1), programmed death ligand 1 (PD‐L1) and cytotoxic T lymphocyte associated protein 4 (CTLA4), which mediate critical pathway responsible of immune-tolerance against tumor cells, are the major therapeutic target of ICIs therapy." (PMID 36159976, 2022). "CTLA-4 blocking antibodies also could hinder tumor growth at the early stage of murine mesothelioma." (PMID 35392976, 2022). "cGAMP combined with anti-CTLA4 and anti-PD-1 mAb treatment inhibits tumor growth." (PMID 35844623, 2022). "A significantly higher tracer uptake was seen in the tumors and spleens of CT26 mice treated with anti-PD-1/anti-CTLA-4 than in a control group, and post-treatment tracer accumulation correlated with a decrease in tumor volume in wild-type mice treated with ICI." (PMID 35625811, 2022). "Finally, as immunotherapy is emerging as a critical breakthrough for tumor treatment, immune checkpoint genes, such as PDL1 and CTLA4, were compared among the two different risk groups." (PMID 35053610, 2022). "In addition, in this study the expression of HLA family members and several immunotherapy-related target genes, such as CD274 (PD-L1), CTLA-4, and LAG-3, was elevated in the tumor environment of the high-risk group compared with the low-risk group." (PMID 36081499, 2022). "Treatment with CTLA-4 blockers significantly enhances anti-tumour immunity." (PMID 36569832, 2022). "Butyrate may inhibit the capacity of DCs to promote tumor-specific T cells, thereby limiting the efficacy of anti-CTLA-4 blockade." (PMID 35677057, 2022). "Anti-CTLA-4 mediates its anti-tumour activity in part, by depleting tumour-infiltrating Tregs33,35." (PMID 35288635, 2022). "In order to validate whether CTLA4-PD-L1 DNA or Protein vaccine acts as a tumor vaccine for iCCA, these reagents were injected before iCCA induction by TAA, i.e., in a preventive setting." (PMID 36341387, 2022). "Similarly, the combination of T-VEC with an anti-CTLA-4 ICI resulted in increased tumor-specific CD8+ T cells and systemic efficacy in A20 and CT-26 contralateral murine tumor models." (PMID 35740539, 2022). "Allison’s group provided definitive evidence to support CTLA-4′s role as a critical immune checkpoint that could be inhibited to enhance anti-tumor immunity." (PMID 35626053, 2022). "To further investigate the relationship between KIRP tumor immunity, we performed the correlation analysis between KIRP immune checkpoint genes (CTLA4, HAVCR2, PDCD1, PDCD1LG2, and TIGIT) and high mutation frequency genes (TTN, MET, KMT2C, PKHD1, SETD2, and KMT2D)." (PMID 36618928, 2022). "Due to that CD80/CD86-CTLA4 axis were involved in the crosstalk between myeloid cells and T cells, and that the application of CTLA4 blockade has been widespread in tumor immunotherapy, we investigated the value of targeting CD80/CD86-CTLA4 axis under inflammatory conditions." (PMID 36443332, 2022). "High accumulation of Tregs expressing CTLA-4 and PD-1 in TDLNs is associated with lymph node involvement, but not with the size of the primary tumour." (PMID 35714487, 2022). "Furthermore, while anti-PD1/CTLA4 alone resulted in no cures, the combination of live stressed/injured tumor cells plus immune checkpoint blockade resulted in a permanent cancer cure in nearly half of the treated animals." (PMID 35402699, 2022). "Therefore, CTLA-4 blockade enhances T cell anti-tumor response and consequently improves clinical outcomes in some cancer types." (PMID 36466910, 2022). "In this regard, TRM lymphocytes have been reported to express molecules involved in cytotoxic activities, such as granzyme B, perforin, IL-2 and IFN-γ, as well as exhaustion markers such as PD-1 and CTLA-4, likely representing tumor-specific effector cells induced by virus antigens." (PMID 36123711, 2022). "In addition, cluster 2 is more responsive to anti-PD-1 and anti-CTLA4 treatments, which indicates that cluster 2 is an immune-favorable tumor." (PMID 35693827, 2022).
tumor (continued). "Notably, a combination of immunotherapy using the vaccine and anti-CTLA-4 monoclonal antibody was found to significantly enhance anti-tumor immune response, relative to mRNA or monoclonal antibody therapies alone." (PMID 35664731, 2022). "In addition, the enrichment of CAF-S1 was correlated positively with PD-1+ and CTLA-4+ CD4+ T cell content but negatively with CD8+ T cells infiltration in tumor." (PMID 36324128, 2022). "The density of α-smooth muscle actin (α-SMA) (a marker of TAFs) and CD31 (a marker for tumor vasculature) in the nanovaccine and anti-CTLA-4 mAb groups was lower than that of the PBS group, whereas the density of CD8 (a marker for CD8+ T cells) was higher than that of the PBS group." (PMID 34875483, 2022). "The inhibitors of PD-1 and CTLA-4 could activate immune response of tumor cells in clinical trials of different cancer types, including pancreatic cancer." (PMID 35800432, 2022). "This is an understudied area, and it may be possible that some of the changes such as expression of immune checkpoint inhibitors like OX40L and CTLA4 appear earlier in TAS versus tumor." (PMID 36230846, 2022). "There exists a wide range of novel ICs that might also present viable therapeutic targets outside of the well-known PD-1 and CTLA-4 IC axes to stimulate anti-tumour immunity in these patients." (PMID 35366537, 2022). "Our current study explains how the efficacy of anti-CTLA-4 might be increased with Pulsed XRT in order to control tumor burden and generate immune memory." (PMID 36275767, 2022). "We treated four non-small-cell lung carcinoma (NSCLC) tumor digests ex vivo with the anti-PD-L1 antibody durvalumab (D) alone or in combination with the anti-CTLA-4 antibody tremelimumab (T) to explore changes in gene and protein expression associated with these ICB therapies." (PMID 34623465, 2022). "Interestingly, both KCC2 and NKCC1 are significantly related to tumor-infiltrating immune cells, including tumor purity and immune checkpoint molecules such as PD-L1, CTLA-4, LAG-3, and TIGIT in ccRCC." (PMID 35372048, 2022). "Compared with the two fractionation regimens of 20 Gy×1 and 6 Gy×5, three fractions of 8 Gy are more effective in the induction of the “abscopal effect”, referring to tumor regression observed outside of the radiation field, and tumor-specific T cells in combination with CTLA-4 blockade." (PMID 36139006, 2022). "Notably, 7HP349 alone induced increased LFA-1 expression in tumor-infiltrating CD8+ Teffs to levels seen with anti–CTLA-4 alone." (PMID 35552271, 2022). "Furthermore, the HIF-1α inhibition with echinomycin synergistically increased the immunotherapeutic effects of anti-CTLA-4 antibodies in mouse tumor models." (PMID 35805044, 2022). "In addition, anti-CTLA-4 increases the intra-tumoral Teffector: Treg ratio by promoting the expansion of ICOS+ effector T-cells in favor of anti-tumor activity." (PMID 35326731, 2022). "However, in mice with colorectal cancer treated with immune checkpoint blockade therapies (including CTLA-4 and anti-PD-L1), B. pseudolongum was isolated from the tumor." (PMID 36733391, 2022). "Additionally, the expression of multiple inhibitory receptors such as CTLA-4, TIGIT, LAG3, PD-1, and PD-L1 suggests that the tumor-acquired resistance was associated with T cell exhaustion in BCG-induced HLA-I+ tumors." (PMID 35503263, 2022). "Tumor infiltrating immune cell profile analyses also revealed the reduction of immuno-suppressive CTLA-4+CD8+ cells and CD4+CD25+Foxp3+ Tregs, whereas the percentage of tumor infiltrating cytotoxic CD8+ T cells and the ratio of M1/M2 macrophages increased in nCHI3L1 Ab treatment group." (PMID 34987649, 2022). "Furthermore, ipilimumab reduced tumor burden in human CTLA4 knock-in mice transplanted with MC38 tumors, but this effect was inhibited with the co-administration of anti-FcR." (PMID 35326731, 2022).
tumor (continued). "In addition, the correlation between LOXL2 expression and immune checkpoint markers (CD274, PDCD1, and CTLA-4) suggested a role for LOXL2 in immune regulation of tumor immunity." (PMID 36254230, 2022). "The combination of the PD-1/CTLA-4 antibody has strongly affected tumor treatment." (PMID 35401745, 2022). "Comprehensive public databases and the data in our group found that the abnormal SWI/SNF subunit PBRM1 was closely related to tumor immune microenvironment-related factors, such as high expression of the immunosuppressive molecules PD-L1 and CTLA4, high sTIL, and iTIL." (PMID 35928964, 2022). "Inhibition of HDAC, PD-1, and CTLA-4 can lead to complete tumor rejection." (PMID 35140720, 2022). "Immunotherapies deploying inhibitors of programmed death-1 (PD-1), programmed death ligand-1 (PD-L1), and cytotoxic T lymphocyte antigen 4 (CTLA-4) are important in the treatment of gastric cancer patients, especially in advanced cases, but unfortunately they have poor efficacy for this tumor type." (PMID 35647201, 2022). "In addition, low scores were linked to high tumor mutation burden, MSI-H and high CTLA4 expression, showing a higher immune cell proportion score (IPS)." (PMID 36248908, 2022). "The study indicated that the intratumoral fibrosis level was negatively correlated with the expression of CTLA4 in the tumor immune microenvironment of the ccRCC, which posed the potential value of targeting the stroma of the tumor, a supplement to immunotherapy." (PMID 35710350, 2022). "HSP90 inhibition also showed to potentiate anti-tumor activity of PD-1 and CTLA-4 blockade in vivo." (PMID 35572591, 2022). "The neutralization of CTLA-4 or PD-1, or even PD-L1, should promote an anti-tumor immune response." (PMID 36513991, 2022). "Experiments using a mouse tumor model showed that the antitumor effect of CTLA4 Abs can be abolished by an antibiotic cocktail or the use of GF mice, which suggested that gut bacterial flora were required for the efficacy of CTLA4 Abs against tumors." (PMID 36429112, 2022). "CTLA-4 is shown to regulate T-cell proliferation early in an immune response, primarily in lymph nodes, whereas PD-1 suppresses T cells later in an immune response, primarily in the tumor tissues." (PMID 35741331, 2022). "It has been demonstrated in a variety of tumor models, including CRC models, that activation of CAF may induce PD-1 and CTLA-4 expression on relevant immune cells, which leads to tumor insensitivity to immunotherapy or recurrence." (PMID 35740594, 2022). "Here the authors report the design of a micelle-releasing thermosensitive hydrogel system for the concomitant locoregional and lymphatic delivery of a nitric oxide donor and an anti-CTLA4 antibody, showing anti-tumor immune responses in preclinical cancer models." (PMID 35304456, 2022). "We observed that the four treatment schedules with anti-CTLA-4 induced significant decrease of tumor growth starting from day 17 with the treatment at days 3, 6, 9, at days 3, 6, 9, 12, and at days 6, 9, 12 whereas starting from day 22 for treatment at days 9, 12, 15, 18 was not effective." (PMID 35339889, 2022). "Additionally, another pan-cancer scoring scheme, namely, immunophenoscore, was built using machine learning to identify determinants of tumor immunogenicity for response to anti-cytotoxic T lymphocyte antigen-4 (CTLA-4) and anti-PD-1 therapy." (PMID 35603201, 2022). "Tim-3 can induce a tumor microenvironment dominated by immunosuppression by functional suppression and exhaustion of T cells and synergistic expressions of Foxp3, CTLA-4, and other harmful immunoregulatory molecules to further attenuate the function of T cells in tumor-killing." (PMID 35958924, 2022). "ICIs enhance T cell activity by blocking CTLA-4, PD-1, or PD-L1 to achieve an anti-tumor effect." (PMID 35962453, 2022). "Inhibition of CTLA-4 can eliminate immune tolerance and tumor cell proliferation." (PMID 36171887, 2022).
tumor (continued). "Interestingly, this study showed that ccRCC with higher intratumor fibrosis was accompanied by more cytokines secretion and the immunosuppressive tumor microenvironment, consisting of less expression of CTLA4." (PMID 35710350, 2022). "Anti-CTLA4 treatment was associated with a coordinated “spike” in effector/memory (CD44highCD62L−) CD8 T cells around day 14 (b top row), following treatment completion (day 12) and coinciding with the start of tumor rejection." (PMID 36230753, 2022). "Moreover, CTLA4/miR-20b-5p axis was revealed to induce immune cell infiltration in the KIRC tumor niche." (PMID 36551549, 2022). "Just recently, we already demonstrated how injectable hydrogels based on poloxamer 407 could significantly reduce the systemic spread of anti-CTLA-4 antibody whilst facilitating effective tumor growth inhibition." (PMID 35890247, 2022). "LC4 peptide could effectively block the CTLA-4/B7 protein interactions, activate peripheral immune organ activity while activating T cell activity in tumour tissues." (PMID 36195696, 2022). "Besides CTLA-4, the Programmed Death 1 receptor and its ligand (PD-1/PD-L1) are an IC that was discovered in 1992 by Tasuku Honjo in a mouse T-cell hybrid tumor." (PMID 36248998, 2022). "LAG-3 has become a novel tumor immunotherapy target beyond CTLA-4 and PD-1/PD-L1." (PMID 35958563, 2022). "Similarly, PD-1 and CTLA-4 are frequently expressed by various immune cells in the tumor microenvironment (TME) and negatively regulate the functions of effector T cells." (PMID 35173722, 2022). "In addition, since FREM2 mutation was associated with immune infiltration, we analyzed its association with the expression levels of PDCD1, CD274, CTLA4, LAG3, TIGIT, and HAVCR2, which are important immune checkpoints responsible for tumor immune escape." (PMID 35252356, 2022). "Cytotoxic T-lymphocyte-associated antigen 4 (CTLA-4), programmed death 1 (PD-1), and programmed cell death 1 ligand 1 (PD-L1) inhibitors had shown good safety and efficacy in various tumor types, including genitourinary oncology, gastrointestinal oncology, and hematologic tumor." (PMID 36212460, 2022). "The most studied checkpoint receptors in tumor immunotherapy targets are cytotoxic T lymphocyte antigen-4 (CTLA-4) and the programmed death-1 (PD-1) receptor, which downregulates the activation, proliferation, and function of T cells through different mechanisms." (PMID 36303158, 2022). "In tumor immunotherapy, the most studied immune checkpoints are the co-inhibitory molecules: programmed death receptor 1/programmed death-ligand 1 (PD1/PD-L1) and cytotoxic T-lymphocyte-associated protein 4 (CTLA-4)." (PMID 35651605, 2022). "Here the authors describe the design of the fusion therapeutic davoceticept (ALPN-202), based on a variant CD80 extracellular domain engineered to bind PD-L1 as well as CD28 and CTLA-4, providing direct T cell costimulation and dual checkpoint inhibition to enable anti-tumor immune responses." (PMID 35379805, 2022). "Correspondingly developed immune checkpoint inhibitors (ICIs), such as anti-PD1/PD-L1 and anti-CTLA-4 can block the interaction between tumor cells that express immune checkpoint molecules and immune cells, thereby blocking the inhibition of tumor cells to immune cells." (PMID 35651605, 2022). "In a large in vivo study, GZP accumulation in the tumor had an overall positive predictive value of 84% for anti-PD-1 and anti-CTLA-4 immunotherapy response in the murine colon cell lines CT26 and MC38-tumor- bearing mice (N=31) and a negative predictive value of 94% (N=35)." (PMID 35625811, 2022). "Moreover, the enhanced anti-tumor effect of combination treatment was correlated with a decrease in the frequency of Tregs compared to treatment with PD-1/CTLA-4 inhibitors." (PMID 36605208, 2022). "In the clinic, the mechanism of anti-tumor efficacy of anti-CTLA-4 therapy is still under debate." (PMID 35237846, 2022).
tumor (continued). "Finally, a model of tumor–immune interaction based on a system of ordinary differential equations revealed how the characteristic dynamics of PD-1 and CTLA-4 activation potentially imposes limitations on the tumor response to PD-1 blockade." (PMID 36428963, 2022). "In sum, these studies highlight that bispecific antibodies that simultaneously target CHI3L1 and CTLA-4 have prominent additive or synergistic anti-tumor effects in vivo and in vitro via its ability to induce CD8+ cytotoxic T cells and enhance tumor cell expression of PTEN." (PMID 36618349, 2022). "Upon cancer progression, different immune escape mechanisms take place, including the onset of tolerance to cancer-associated antigens (especially when similar to natural antigens) and overexpression of CTLA-4, PD-1, or PD-L1, to inhibit the cytotoxic effect of CTLs on tumor cells." (PMID 35626078, 2022). "The CD8+ PBMC cluster of Pop3 and Pop4 and CD4eff PBMC cluster of Pop0 and Pop4 were distinctly different to the other tissue types with lower expression of checkpoint markers (PD-1, ICOS, and CTLA-4), suggesting a less regulated immune tumor environment in the periphery." (PMID 35320356, 2022). "Beyond CTLA-4 and PD-L1/PD1, one target that is actively being studied is the lymphocyte activation gene-3 (LAG-3), which has been associated with the exhaustion of tumour-infiltrating T cells, as a mechanism of resistance to certain immunotherapies." (PMID 36297474, 2022). "This study is aimed for a comparative analysis of CTLA-4+ cells between different tumor entities." (PMID 35091676, 2022). "However, neoantigen vaccines spontaneously upregulate the expression of surface molecules (such as PD-1, TIM3 and CTLA-4) in neoantigen-specific T cells and/or PD-L1 in tumor cells, which in turn impedes the function of the neoantigen vaccines." (PMID 36439494, 2022). "Combined immunotherapy or anti-CTLA4 dose escalation afforded improved tumor control." (PMID 36230753, 2022). "LC4-PLG-RGD as a result has better anti-tumour effect, could reduce peripheral immune system activation, and reduce irAEs produced in CTLA-4 treatment." (PMID 36195696, 2022). "Blocking of CTLA-4 with tremelimumab allows T cells to proliferate and attack tumor cells." (PMID 35625837, 2022). "It has shown potent antitumor activity in combination with CTLA4 blockers in tumor immunotherapy." (PMID 36405706, 2022). "Furthermore, CTLA-4 is constitutively expressed on Tregs and thus plays an essential role in maintaining the immunosuppressive environment within the tumour microenvironment." (PMID 35326677, 2022). "CTP reduces the levels of PD-1, PD-L1, and CTLA4 in ApcMin/+ mice, which have been confirmed to regulate the immune reactivity of tumor cells, and antibodies against PD-1 and PD-L1 have been successfully used for tumor therapy." (PMID 35662701, 2022). "Moreover, it has been reported that CTLA-4 inhibition favours the expansion of PD-1-expressing tumour-infiltrating lymphocytes, whereas the inhibition of PD-1 leads to the upregulation of CTLA-4 in these cells." (PMID 35207291, 2022). "Growing evidence that a favorable microbiota may increase the efficacy of anti-PD-L1 and anti-CTLA-4 therapies by activating dendritic cell (DC) activation, leading to further anti-tumor T cell response." (PMID 35474500, 2022). "The TIDE score has been identified as a potent biomarker to predict the tumor response to anti-PD1 or anti-CTLA4, while the TMB score has also been validated as an available tool to help oncologists select patients who may benefit from ICIs." (PMID 36212161, 2022). "Our results showed that high level of PD1, PD-L1 and CTLA4 was observed in TNBC patients with low IRGriskscore, which strongly implicated that TNBC patients with low IRGriskscore might be suitable for anti-tumor immunotherapy." (PMID 36358906, 2022).